DYRK1A (dual specificity tyrosine phosphorylation regulated kinase 1A)
Diseases named in the same sentence as DYRK1A in open-access papers (continued):
Sharing a sentence is not in itself a finding about the gene and the disease.
Alzheimer disease (continued). "It is thus no surprise that neurological syndromes and disorders such as DS, Alzheimer’s disease, Parkinson’s, and Pick’s disease all involve abnormal expression of DYRK1A." (PMID 34832952, 2021). "In a recent study, novel prodrugs for Alzheimer’s disease targeting 2 specific targets, dual-specificity tyrosine phosphorylation-regulated kinase 1A (DYRK1A) and cholinesterase (ChE), were designed and synthesized." (PMID 32443905, 2020). "Overexpression of DYRK1A is also involved in the formation of the neurotoxic β-amyloid plaques and hyperphosphorylation of the tau-protein as seen in Alzheimer’s disease." (PMID 31766108, 2019). "Recent evidences suggest the involvement of DYRK1A (dual specificity tyrosine phosphorylation-regulated kinase 1 A) in Alzheimer’s disease (AD)." (PMID 30885273, 2019). "Recently, a novel inhibitor of DYRK1A has been shown to reduce amyloid-β plaque load in an Alzheimer’s disease mouse model." (PMID 29945247, 2018). "DYRK1A was considered to play important roles in the pathogenesis of DS and Alzheimer's disease; however, the degradation mechanism of DYRK1A was still unclear." (PMID 27807027, 2016). "Intriguingly, increased DYRK1A activity has been also reported in various brain compartments in subjects that suffer from Alzheimer's disease (AD), a representative neurodegenerative disease." (PMID 27483355, 2016). "A dual-specificity kinase DYRK1A, an importance of which has been highlighted in Alzheimer’s disease, was targeted in this study." (PMID 26234946, 2015). "Dual specificity tyrosine-phosphorylation-regulated kinase-1A (DYRK1A) is an enzyme directly involved in Alzheimer’s disease, since its increased expression leads to β-amyloidosis, Tau protein aggregation, and subsequent formation of neurofibrillary tangles." (PMID 25756379, 2015). "In a follow-up study, the authors confirmed these observations and suggested that such reduced interaction between DYRK1A and cytoskeletal proteins may constitute an early biomarker for the diagnosis of Alzheimer’s disease from PMBCs." (PMID 40519271, 2025). "Imaging of DYRK1A may provide an earlier biomarker for Tauopathies, including Alzheimer’s disease (AD)." (PMID 40076215, 2025). "In neurological diseases, miR‐26a‐5p could target DYRK1A to inhibits Tau phosphorylation and Aβ accumulation, which ameliorated the cognitive dysfunction, in Alzheimer's disease mice." (PMID 36756710, 2023). "Consequently, DYRK1A has been considered as a potential therapeutic target of neurodegenerative diseases such as Alzheimer’s disease (AD) and Down’s syndrome (DS)." (PMID 35335117, 2022). "Moreover, in humans, a member of the DYRK1 subgroup, DYRK1A, induced the destabilization of microtubules via the hyperphosphorylation of tau proteins, which is a causal agent of Alzheimer’s disease." (PMID 34549353, 2021). "In this context, our research group is mainly invested in the synthesis of C,N,S-containing bioactive molecules able to modulate the activity of deregulated kinases (CDK5, GSK-3, CLK1, CK1 and the dual-specificity kinase DYRK1A) involved to some extent in Alzheimer’s disease (AD)." (PMID 27322235, 2016). "However, the effects of direct genetic manipulation of DYRK1A in the brain on cognitive function, neuroinflammation and Alzheimer’s disease (AD) pathology and underlying molecular mechanisms have not been fully investigated." (PMID 41306975, 2025). "FAM53C, by suppressing DYRK1A activity, may possibly also be involved in Alzheimer disease." (PMID 37802655, 2023). "Furthermore, several synthetic meridianin analogs showed potent and selective inhibitory effects over glycogen synthase-3 (GSK-3) and dual-specificity tyrosine-phosphorylation regulated kinase 1A (DYRK-1A), which are known to be implicated in the progression of Alzheimer’s disease." (PMID 34572319, 2021).
Alzheimer disease (continued). "Aristolactams AII, BII, and velutinam were evaluated for their ability to inhibit DYRK1A and CDK1/cyclin B kinases, that are related with neurodegenerative disorders, like Alzheimer's disease." (PMID 41494962, 2026). "Trisomy 21 (T21) confers increased gene dosage of the amyloid precursor protein (APP) and other proteins (BACE2, S100β, DYRK1A, RCAN1) involved in Alzheimer's disease (AD) pathology." (PMID 40536124, 2025). "Kinase inhibition of the final compounds was evaluated on a panel of four Ser/Thr kinases (DYRK1A, CDK5, CK1 and GSK3) chosen for their strong implications in various regulation processes, especially Alzheimer’s disease (AD)." (PMID 25268714, 2014). "Among them, harmine has been reported to inhibit MAO, AChE, and dual-specificity tyrosine-phosphorylation-regulated kinase 1A (DYRK1A), thereby exerting various pharmacological effects, including antitumor, antioxidant, anti-inflammatory, anti-Alzheimer’s disease and antidepressant effects." (PMID 40693273, 2025). "Phosphorylation by DYRK1A at tau Thr212 residue primes tau phosphorylation by GSK3 at the Ser208 residue, resulting in increased neurofibrillary accumulation tangles exists in the brain of Alzheimer’s Disease patients." (PMID 34445786, 2021). "Interestingly, DYRK1A and RCAN1 contribute to the learning and memory deficit, altered synaptic plasticity, impaired cell cycle regulation, and Alzheimer Disease-like neuropathology in DS." (PMID 25767303, 2014). "Interestingly, DYRK1A protein has been found to be associated with neurofibrillary tangles (NFTs) in sporadic Alzheimer's disease and some studies have found a genetic association between SNPs within the DYRK1A locus and Alzheimer's disease in some populations but not others." (PMID 21573099, 2011). "↓ of kinase expression (5 μM): GSK3β, CDK5, DYRK1A, CAMK2A, MAPK1, MAPK12, MAPK14.Modulation of the hGMSC transcriptome, ↓ expression of genes involved in Alzheimer's pathogenesis.↓ expression of GSK3b and p‐GSK303B2, which plays a key role in Alzheimer's disease." (PMID 39653426, 2025). "Thus, Dyrk1A might be an ideal therapeutic target for Alzheimer’s disease, especially for Down syndrome and EGCG which inhibits Dyrk1A may have potential effect on the treatment or prevention of this disease." (PMID 28377597, 2017).
cognitive deficits (58 papers, 2009 to 2025). "In contrast, AHI1 deficiency promotes the binding of DYRK1A to Dcaf7, which leads to elevated DYRK1A, reduced synaptic plasticity, and cognitive deficits." (PMID 38975245, 2024). "The brains of AD patients and mouse models of AD with cognitive impairment show increased DYRK1A levels, which are associated with increased Tau phosphorylation that can be reversed with DYRK1A inhibitors." (PMID 37015911, 2023). "It has been proposed that Dyrk1A, which is located within the genomic DS critical region on human chromosome 21, is implicated in the cognitive impairments seen in DS." (PMID 34090874, 2021). "DYRK1A involvement in cognitive deficits associated with various neurodegenerative disorders brought medicinal chemists to a long-standing interest in developing selective DYRK1A inhibitors to treat complex and unmet medical needs." (PMID 34445804, 2021). "Nevertheless, all available results clearly demonstrate the implication of DYRK1A in DS intellectual deficiencies and the beneficial effects of its inhibition on the correction of cognitive deficits." (PMID 30115750, 2018). "Modulation of DYRK1A in MRD7 by increasing its activity would be a good strategy to alleviate the severe cognitive deficits present in the disease, in particular for loss-of-function mutations." (PMID 27375444, 2016). "Therefore, a therapeutic strategy for cognitive deficits associated with DS, and ultimately AD, would involve controlled inhibition of brain DYRK1A activity." (PMID 34445786, 2021). "Among the candidate genes for cognitive impairment in DS, DYRK1A which encodes the dual-specificity tyrosine-(Y)-phosphorylation-regulated kinase 1A protein, has received increasing attention, considering its involvement in the neurodevelopment of numerous species." (PMID 30332747, 2018). "Moreover, pathological mutations in DYRK1A cause phenotypic outcomes (autism, seizures, cognitive impairment) and molecular defects (neural progenitor proliferation, microtubule dynamics, dendritic development, spine maturation) that greatly overlap with those linked to CDKL5." (PMID 32032735, 2020). "As DYRK1A is a high-risk gene for ASD, previously identified genetic interaction between DSCAM and DYRK1A in DS mice sheds light on a link between DS and ASD, implicating an association of DSCAM with cognitive deficits in ASD." (PMID 40385132, 2025). "In fact, pharmacological inhibition of DYRK1A reduces Aβ and tau pathology and improves AD-related cognitive impairments in mouse models of AD, delaying the onset of both Aβ plaques and tau-containing neurofibrillary tangles (NFTs)." (PMID 40664536, 2025). "Overexpression of Dyrk1a during crucial developmental stages likely contributes to DS-related phenotypes such as cognitive impairment, skeletal deficits and craniofacial abnormalities." (PMID 39136051, 2024). "Blocking the enzyme DYRK1A has been identified as a potential therapy strategy, as studies have shown that DYRK1A inhibitors can improve cognitive impairments in DS animals." (PMID 39204195, 2024). "In conclusion, ASOs targeting DYRK1A would not only aid in mitigating the cognitive deficits from DS but also have the potential to address a broader range of neurological and other diseases." (PMID 39114642, 2024). "Several reports describe potential DYRK1A inhibitors and their possible use for correcting DS-related cognitive deficits." (PMID 39136051, 2024). "The second model (TgDyrk1A), overexpresses only the dual-specificity tyrosine phosphorylation-regulated kinase 1a (Dyrk1a), a gene whose overexpression recapitulates the main neuronal architecture defects and cognitive impairments of the trisomy." (PMID 38968294, 2024). "DYRK1A-related neurological diseases show some clinical symptoms such as cognitive disorder with learning and memory impairment." (PMID 36830653, 2023).
cognitive deficits (continued). "Increasing DYRK1A activity would be a potential strategy to alleviate the severe cognitive deficits present in MRD7 and by extrapolation, other pathologies with an autistic spectrum." (PMID 36012629, 2022). "One such candidate gene is DYRK1A, which is highly expressed throughout the brain and further so in DS36,37, contributing to motor and cognitive deficits associated with the disease." (PMID 36151233, 2022). "The overexpression of DYRK1A plays a principal role in cognitive deficits in people suffering from AD." (PMID 36741918, 2022). "Transgenic mice with either excess or haploinsufficiency of Dyrk1a show cognitive deficits like those observed in patients with specific impairment of hippocampal-dependent learning and memory." (PMID 34587162, 2021). "DYRK1A is definitely a main gene driver of cognitive impairment in DS models, and DYRK1A inhibitors have emerged as a promising therapeutic path to reduce DS cognitive deficits in adults but also after in utero treatment in animal models." (PMID 34828439, 2021). "DYRK1A, a gene found in three copies of most DS mouse models and individuals with DS, is a candidate gene for cognitive impairment, Alzheimer-like phenotypes, and skeletal abnormalities related to DS." (PMID 34828335, 2021). "There is considerable genetical and pharmacological evidence showing that the mere 1.5-fold overexpression of DYRK1A is responsible for most cognitive deficits observed in DS patients (reviews:)." (PMID 34205123, 2021). "The potential roles of DYRK1A on cognitive deficits in individuals with DS has recently been reviewed suggesting that DYRK1A plays a key role in controlling cellular growth, neurogenesis and neuronal maturation." (PMID 34832952, 2021). "These are examples of different biological brain functions controlled by DYRK1A which are probably dysregulated when DYRK1A is overexpressed in DS, leading to cognitive impairments." (PMID 30115750, 2018). "Overexpression of the Dual-specificity Tyrosine Phosphorylation-Regulated Kinase 1A (DYRK1A) gene contributes to the retardation, cognitive impairment, and learning and memory deficits associated with DS." (PMID 30496304, 2018). "Treatment of the three DS models with the pharmacological DYRK1A inhibitor leucettine L41 leads to normalization of DYRK1A activity and corrects the novel object cognitive impairment observed in these models." (PMID 30115750, 2018). "These facts provide additional incentive to investigate the regulation and substrates of brain DYRK1A and to develop potent and selective DYRK1A inhibitors to treat cognitive deficits observed in different indications." (PMID 30115750, 2018). "DYRK1A, a dual specificity kinase expressed during early neurogenesis that has been a target in pilot studies for treatment of cognitive deficits in DS, also produced no phenotype." (PMID 29760202, 2018). "DYRK1A haploinsufficiency results in a clinical phenotype which includes microcephaly, intellectual impairment, the presence of vision and motor difficulties, feeding difficulties, language delays, and ASD risk." (PMID 29034068, 2017). "Among the genes from this region, Dyrk1a was an attractive candidate for inducing cognitive-impairment phenotypes." (PMID 28993310, 2017). "Undeniably DYRK1A inhibitors represent a promising class of molecules to improve cognitive deficits in people with DS." (PMID 27375444, 2016). "Among the different approaches, DYRK1A inhibitors have emerged as promising therapeutics to reduce DS cognitive deficits." (PMID 27375444, 2016). "Using a novel object recognition paradigm to assess long term memory, transgenic mice with three copies of DYRK1A were clearly impaired: polyphenol treatment ameliorates cognitive deficits in tgYAC152F7 mice." (PMID 19242551, 2009). "Similarly, experiments crossing Dp1Yey with Dyrk1a+/− mice or pharmacologically inhibiting brain DYRK1A corrected cognitive deficits." (PMID 40333415, 2025).
cognitive deficits (continued). "Interestingly, a recovery in the developmental cognitive deficit was reported after a partial rescue of DYRK1A in DS mice." (PMID 39114642, 2024). "Moreover, treatment with sPIF restored the level of DYRK1A, a protein that is involved in cognitive impairments in DS." (PMID 38739166, 2024). "Trisomic Dyrk1a has been hypothesized to contribute to both cognitive impairment and skeletal development." (PMID 34828335, 2021). "This is an important result that may, in part, explain why most of the current competitive Dyrk1a inhibitors fail to pass the pre-clinical stage with respect to improvement of cognitive impairments in DS." (PMID 31995755, 2020). "Similarly, employment of DYRK1A inhibitors to target cognitive deficits in DS and β-cell dysfunction in diabetes is a rapidly developing field." (PMID 31086297, 2019). "In light of the encouraging preclinical data reported by our group and others, which provide compelling evidence for the role of DYRK1A signalling in the cognitive impairment in DS, it has indeed become a viable option to initiate testing of DYRK1A inhibitors in the clinical setting." (PMID 30332747, 2018). "Interestingly, epigallocatechin gallate (ECGC), a natural polyphenol found in green tea leaves and is a specific inhibitor of DYRK1A, has been shown to attenuate cognitive defects arising from DYRK1A over-expression in transgenic mice." (PMID 23554618, 2010). "Therefore, combining genetic knockdown of DYRK1A with a tau inhibitor might have synergistic effects on multiple aspects of AD pathology, including cognitive impairment, neuroinflammation, and Aβ/tau pathology." (PMID 41306975, 2025). "In addition, DYRK1A knockdown directly in the hippocampus in Aβ-overexpressing 5xFAD mice significantly attenuated cognitive impairment and neuroinflammatory responses, increased anti-oxidative/anti-inflammatory HO-1 levels, and reduced Aβ pathology by suppressing BACE-1 activity." (PMID 41306975, 2025). "Therefore, the DYRK1A gene likely plays an important role in the cognitive deficits found in DS." (PMID 25188425, 2014). "A recent highly potent and specific ATP-binding site small molecule DYRK1A inhibitor has been reported that crosses the blood brain barrier with 1 and 100 μM PST-001 significantly reducing DYRK1A activity reversing cognitive deficits of mouse DS models." (PMID 35928283, 2022). "Further analysis of DYRK1A impact on other neurons, such as GABAergic ones, will be necessary to understand how DYRK1A perturbs the excitatory/inhibitory pathways, resulting in the full DS and MRD7 cognitive deficits." (PMID 34587162, 2021). "Our finding outlines the glutamatergic deficit as a distinct alteration with Dyrk1a overexpression playing a key role in glutamatergic dysfunction and GABA-mediated over-inhibition combining with it to produce the full DS cognitive deficit." (PMID 34587162, 2021). "DYRK1A overexpression varies based on tissue and age, which means treating cognitive deficits could worsen bone, as evidenced by previous EGCG treatments." (PMID 41377504, 2025). "OLIG2, SIM2, S100B, SOD1, DYRK1A, APP, and GADT3A are involved in axonal proliferation and neurite extension, and overactivity of this group of genes may be responsible for cognitive impairment." (PMID 35676933, 2022). "Taken together, these data provide further understanding into the regulation of CBS and in particular into the genetic relationship between DYRK1A and CBS through the Akt/GSK3β and NF-κB pathways, which should help develop more effective therapies to reduce cognitive deficits in people with DS." (PMID 36711154, 2022). "We here establish a proof of concept that pharmacological inhibition of brain DYRK1A is able to correct NOR cognitive impairment in three DS models with increasing genetic complexity." (PMID 30115750, 2018).
cognitive deficits (continued). "Interestingly, the over-expression of DYRK1A can also be modulated by EGCG and transgenic mice overexpressing this gene and presenting cognitive impairment, rescue the cognitive phenotype after a polyphenol-based diet." (PMID 23830204, 2013).